TGFB2 (transforming growth factor beta 2)
Diseases named in the same sentence as TGFB2 in open-access papers (continued):
Sharing a sentence is not in itself a finding about the gene and the disease.
ovarian epithelial tumor (1 paper, 2017). A benign, borderline, or malignant tumor that originates from the surface epithelium of the ovary. "Ovarian epithelial tumor cells showed concurrent up-regulation of miR-200, down-regulation of the four target genes (ZEB1, ZEB2, TGFβ1 and TGFβ2), and up-regulation of effector genes that were negatively regulated by the target genes." (PMID 28623900, 2017).
ovarian hyperstimulation syndrome (1 paper, 2024). A complication of ovulation induction in infertility treatment. "TGFβ1 and TGFβ3, but not TGFβ2, are upregulated in the ovaries of ovarian hyperstimulation syndrome." (PMID 38791596, 2024).
pemphigus (1 paper, 2021). Pemphigus is a group of rare autoimmune diseases that cause blistering of the skin and mucous membranes (mouth, nose, throat, eyes, and genitals).This conditioncan occur at any age, but often strikes people in middle or older age. "Several other skin homeostatic genes, including WIF1, EDA, RXRG, and TGFB2, were significantly decreased in pemphigus cases." (PMID 34660634, 2021).
pituitary tumor (1 paper, 2022). A benign or malignant neoplasm affecting the pituitary gland. "The expression of PDGFA, PDGFB, TGFB1 and TGFB2 in pituitary tumor tissue was respectively 3.5 x104, 2.0 x 104, 1.3 x 105 and 6.6 x 103 copies/μg total RNA." (PMID 35600354, 2022).
psychotic disorder (1 paper, 2024). An abnormal condition of the mind that involves a loss of contact with reality. "Hence, more studies on molecular or environmental events that lead to DNA hypomethylation of TGFB2 promoter may uncover one of the underlying mechanisms of disease pathogenesis in these interlinked psychotic disorders." (PMID 38994948, 2024).
renal agenesis (1 paper, 2017). Renal agenesis (RA) is a form of renal tract malformation characterized by the complete absence of development of one or both kidneys (unilateral RA or bilateral RA respectively), accompanied by absent ureter(s). "Intriguingly, however, Tgfβ2 homozygous mice display renal agenesis, whereas mice lacking activin B die at birth." (PMID 29240767, 2017).
renal tumors (1 paper, 2010). "Notably, several key genes involved in TGF-β signaling, such as TGFB2, INHBA, THBS1 and SMAD3, were down-regulated in FLCN-null and mutant FLCN cells as well as in the BHD-associated renal tumors." (PMID 20573232, 2010). "GREM1, TGFB2, INHBA, THBS1 and SMAD3 RNA expression levels were significantly lower in the BHD renal tumors compared to normal kidney tissue." (PMID 20573232, 2010).
senile cataract (1 paper, 2018). A cataract with no obvious cause occurring in persons over 50 years old. "We found that the concentrations of IL-8, MMP-2, MMP-3, MMP-9, TGFβ-1, TGFβ-2, TGFβ-3, SAA, and TNF-α were significantly elevated in JIAU samples compared with the control group (senile cataract patients)." (PMID 29675026, 2018).
skin melanomas (1 paper, 2007). "Nevertheless, despite cessation of TGFβ2 production, the tolerogenic DCs are still present in numbers comparable with primary skin melanomas." (PMID 17565341, 2007).
spondylolisthesis (1 paper, 2025). A condition in which there is forward displacement of a vertebral bone over the on below it. "The predominant NPPCs in C2 exhibit osteogenic features, with high expression of genes such as BMP4, TGFB2, and THBS1, indicating an adaptive response to spinal instability, which is often linked with spondylolisthesis." (PMID 40883814, 2025).
Spontaneous pneumothorax (1 paper, 2019). Pneumothorax occurring without traumatic injury to the chest or lung. "Additional features included spontaneous pneumothorax in SMAD3-related LDS and cervical spine instability in TGFB2-related LDS." (PMID 31569402, 2019).
steatosis (1 paper, 2019). Increased lipid within the cytoplasm of cells. "The up‐regulation of UBE2V1, RP11‐128N14.5, BNIP3L and TGFB2/TGFB2‐OT1 in NAS ≥ 5 vs NAS ≤ 4 patients, RP11‐128N14.5 in NASH vs simple steatosis and the up‐regulation of HBA2, and TGFB2/TGFB2‐OT1 in F = 3‐4 vs F = 0‐2 patients were also confirmed in the external validation cohort." (PMID 31169972, 2019).
synovial sarcoma (1 paper, 2006). "Additionally, many other genes that have been previously related to synovial sarcomas, such as the SSX4 gene, EGFR and SALL2, components of the retinoic acid pathway (CRABP1 and RARG) as well as retinoic acid induced genes (IRX5 and TGFβ2), were also included in this module." (PMID 16503973, 2006).
thrombosis (1 paper, 2022). "In our previous study, high expression of inflammatory factor TNFα was accompanied by significant downregulation of TGFβ2 within the venous wall after thrombosis." (PMID 35808901, 2022).
thymic adenocarcinoma (1 paper, 2017).
toxoplasmosis (1 paper, 2022). A parasitic disease contracted by the ingestion or fetal transmission of toxoplasma gondii. "In addition to the TNF pathway, we detected enrichment of candidate genes involved in the toxoplasmosis (TGFβ2/CHUK/CIITA/SOCS1) pathway in the tolerant animals." (PMID 35464478, 2022). "In addition, the TNF-signaling (bta04668; TRAF5/CREB5/CASP7/CHUK) and the toxoplasmosis (bta05145; TGFβ2/CHUK/CIITA/SOCS1) pathways were significantly enriched." (PMID 35464478, 2022).
trachoma (1 paper, 2016). "Full characterization of the role of TGFβ2 in trachoma has been limited due to its complex post-translational modifications." (PMID 27249027, 2016). "Despite having a well-defined role in tissue fibrosis, no previous associations have been found between TGFβ2 and trachoma at both expression and protein levels (Holland, Mabey and Bailey; personal communication)." (PMID 27249027, 2016).
Type 2 diabetes (1 paper, 2021). "Type 2 diabetes is associated with increased APOE, BAX, MMP1, NFKB1, PDGFB, SPP1, and TGFB2." (PMID 35153741, 2021).
ZIKV infection (1 paper, 2019). "Even both of them induced apparent liver inflammation, ZIKV infection showed a more severe inflammatory response than DENV-2 infection based on the inflammation scores and the gene expression levels of IL-1β, TNF, IL-6, and TGFβ-2 in liver." (PMID 31191474, 2019).
tumor (410 papers, 2002 to 2026). "In this study, we analyzed 58 patient tumor samples and observed that expression of the cytokine TGFβ2 was associated with poor responses to FEC." (PMID 39327614, 2024). "Transforming growth factor beta 2 (TGFβ2) secreted by tumor-associated macrophages (TAMs) promotes GC cell invasion by promoting the level of FERMT2." (PMID 38352691, 2024). "In the STAD dataset, patients in the TGFβ2 high expression group had worse tumor grade, and the TGFβ2 methylation score was associated with T stage." (PMID 35620459, 2022). "In CRC, CASC9 is significantly upregulated, and higher CASC9 is associated with tumor progression and poor outcomes by polyadenylation specificity factor subunit 3 and TGFβ2 mRNA." (PMID 35427373, 2022). "Tumor-associated macrophages (TAM) secrete transforming growth factor beta 2 (TGF-β2) to regulate liver leukemia factor (HLF)." (PMID 36467032, 2022). "Data evaluation uncovered some CNAs associated with tumor recurrence, in particular, gain of TGFB2 and gain or loss of TMPRSS2." (PMID 35841413, 2022). "SHH MB subgroup has increased expression of inflammation-related genes (CD14, PTX3, CD4, CD163, CSF1R, and TGFB2) and significantly higher infiltration of tumour-associated fibroblasts than Grp3 MB and Grp4 MB." (PMID 34195095, 2021). "It is now essential that levels of both TGFβ2 and sCTLA-4 are assessed in other cancers associated with increased TGFβ2 levels, especially those that have previously been identified as “cold” tumor types." (PMID 35069536, 2021). "Based on these considerations, the aim of our work was to confirm in a larger cohort of patients the diagnostic performance of PAX3d, MITF-m and TGFB2 circulating tumor transcripts for CMM detection." (PMID 29156734, 2017). "Higher TGFB2 mRNA levels in the primary tumours were associated with better overall survival of patients." (PMID 26703884, 2015). "It is known that many cancer-associated gene products have bifunctional roles in tumor progression and metastasis, for example, TGFβ2 and TGFβR1." (PMID 24369449, 2013). "For instance, elevated levels of TGFB2 are associated with a fibrotic and immunosuppressive tumor microenvironment due to its ability to foster the expansion of cancer-associated fibroblasts (CAFs) and the infiltration of tumor-associated macrophages (TAMs)." (PMID 40650134, 2025). "Tumor mutation burden and neoantigens were both higher in the TGFβ2 low expression group." (PMID 35620459, 2022). "This indicates that TGFβ2 is closely linked with tumour DC penetration." (PMID 32530106, 2020). "Among all of the genes TGFβ2 was emphasized and associated with patients’ prognosis or tumor progression, its expression could be affected by cg11976166." (PMID 33115518, 2020). "Therefore, this current study presented differentially expressed miRNAs and mRNAs related to metastatic OC and revealed a tumor-inhibiting role of miR-7-5p in the restriction of OC metastasis, which was associated with the regulation of TGFβ2." (PMID 33100909, 2020). "Our findings that FAK regulated the transcription of cytokines and chemokines (including Ccl5 and TGFβ2) that were associated with elevated intra-tumoral Tregs and tumor tolerance led us to consider a possible role for nuclear FAK in regulating the transcription of these genes." (PMID 26406376, 2015). "This was confirmed by IHC, which showed that TGFβ2 is primarily tumour cell associated." (PMID 17565341, 2007). "Our results showed that tumor cell-cell contact induced cell proliferation which may represent dormancy escape via activation of β1 integrin associated with universal downregulation of TGFB2 signaling and upregulation of MLCK activation/CDK6 in PCa PDXs." (PMID 26090669, 2015). "We next measured TGFβ2 levels in peripheral blood and tumor interstitial fluid from mEC25 tumor‐bearing C57BL/6N mice." (PMID 41144758, 2026).
tumor (continued). "We classified gene expression profiles into three clusters based on genes that showed a significant TGFB2-dependent influence on OS, specifically those with high expression levels in tumor tissues (a 4-fold or greater increase relative to normal tissue)." (PMID 41465326, 2025). "Our study suggests that the interaction between miR-193b-3p, TGFβ2, and the acidic tumor microenvironment promotes cancer EMT change." (PMID 39992949, 2025). "TGFB2 methylation is a prognostic marker for PDAC patients within an immunosuppressed tumor microenvironment characterized by low CD8+ T-cell infiltration." (PMID 40565031, 2025). "TGFB2 expression increased 1.95-fold in tumor tissues (p < 0.0001), indicating its involvement in tumor pathology." (PMID 41373732, 2025). "The TGFB2-dependency will require additional measurements of mRNA levels of TGFB2 along with the prognostic markers in the cellular compartments of the tumor." (PMID 41465326, 2025). "In conclusion, this study provides new insights into the interactions of miR-193b-3p, TGFβ2, and the acidic conditions such as tumor microenvironment." (PMID 39992949, 2025). "Clinically, higher TGFB2 methylation corresponds to a more robust T cell-mediated immune response and a less mesenchymal, less aggressive tumor, contributing to improved patient survival." (PMID 40650134, 2025). "This silencing likely diminishes the pro-tumorigenic effects that TGFB2 normally exerts—such as promoting a fibrotic and immunosuppressive tumor microenvironment—which in turn correlates with improved OS in younger patients." (PMID 40650134, 2025). "TGFβ2 can play either a protumorigenic or antitumorigenic role at different stages of tumor development, indicating its complex role in cancer biology." (PMID 40151835, 2025). "Younger patients, who retain a more effective pool of cytotoxic T and NK cells, can capitalize on the uncloaked tumor environment following TGFB2 blockade." (PMID 40650134, 2025). "Within the ECM gene category, TGFB2 is upregulated in poor prognosis tumours compared to good prognosis (log2fc = −0.72), highlighting its role in promoting tumour progression." (PMID 41007296, 2025). "Belagenpumatucel-L (Lucanix) is a vaccine generated from irradiated allogeneic NSCLC cells transfected with an antisense TGFβ2 gene plasmid to enhance adaptive anti-tumor immunity while downregulating TGFβ expression." (PMID 41542091, 2025). "We identified three clusters of gene expression profiles that showed a significant TGFB2-dependent impact on OS, with high expression (>4-fold increase) in tumor tissues compared to normal tissues." (PMID 41465326, 2025). "Under acidic tumor microenvironment conditions, a marked increase in TGFβ2 compared to TGFβ1 was observed." (PMID 39992949, 2025). "Taken together, these results suggest that macrophage polarization in the LGG TME can be driven by interferon-gamma activation of the STAT1/IRF1/IRF5 to promote tumor progression in concert with TGFB2 levels." (PMID 38539537, 2024). "To answer that question, we screened the pan-cancer database of the kmplot.com database and selected those neoplasias where at least one member of the overexpression of TGFB2 or TGB3 and TGFBR2 or TGBR3 negatively affected the overall survival." (PMID 38196068, 2024). "Previous studies have established that agents inhibiting the TGFβ2 pathway can impede tumor metastasis." (PMID 38531630, 2024). "In contrast, in tumor tissue, TGFB2 mRNA expression levels are significantly higher, representing a 7.9-fold increase in mRNA expression relative to normal tissue (p < 0.0001)." (PMID 39457004, 2024). "In keeping with a role in driving poor outcome TNBC biology, TGFβ2 has been previously shown to dictate disseminated tumor cell (DTC) fate in target organs." (PMID 39327614, 2024).
tumor (continued). "Our study suggests that treatment options that abrogate the TGFB2 mRNA expression, such as OT-101, combined with the delivery of interferon-gamma to the tumor microenvironment can improve the survival outcomes of pbDMG patients." (PMID 38255296, 2024). "High intra-tumor TGFB2 levels in the upper quartile range of the mRNA expression in the 41 pbDMG patients were associated with poor treatment and overall survival rates." (PMID 38255296, 2024). "In contrast, in tumor tissue, TGFB2 expression levels exhibited a 7.9-fold increase in mRNA expression relative to normal tissue (p < 0.0001)." (PMID 39457004, 2024). "In response to paclitaxel or 5‐Fu treatment, the tumour volume and weight of TGFβ2‐ or Snail1‐knockdown groups decreased significantly more than that of the control group." (PMID 38299307, 2024). "It has been previously reported that imperatorin, a naturally occurring furanocoumarin, exerted a significantly inhibitory effect on TGFB2 expression and it plays a pivotal role in tumor therapy in various cancers." (PMID 38914663, 2024). "LGG patients expressing high levels of TGFB2 and IFNGR2 are over-represented in IDH wild-type tumor samples, suggesting that TGFB2 and IFNGR2 mRNA can be therapeutically targeted in these high-risk patients." (PMID 38539537, 2024). "These patients exhibit features such as BRAF mutations, TGFβ2 mutations, MSI‐H, right‐sided CRC, poor tumor differentiation, and recurrent peritoneal seeding." (PMID 37942534, 2024). "Protumorigenic factors associated with hypoxia and angiogenesis, like HIF1A and VEGFA, as well as genes related to a pro-tumoral phenotype, such as SPP1 and TGFB2, were highly expressed in this macrophage found in the tumor context." (PMID 38972873, 2024). "Although TGFβ can be produced by myeloid cells, mesenchymal cells, and tumour cells via endocrine, paracrine or autocrine manners, the molecular mechanism that controls TGFβ2 expression remains elusive." (PMID 38299307, 2024). "From the PDAC gemcitabine-resistant cells and subcutaneous tumor, the detection of lipid droplets and their components further suggested that silencing TGFB2 reduced neutral lipid accumulation in gemcitabine-resistant PDAC." (PMID 38914663, 2024). "We administered gemcitabine or the TGFB2 inhibitor imperatorin or a combination of both drugs to nude mice and continuously measured tumor size." (PMID 38914663, 2024). "In the present study, we compared the RNAseq-based TGFB2 mRNA levels in primary DIPG tumor samples and normal control pons samples." (PMID 36980562, 2023). "We also analyzed the expression of CD4, CD8, Foxp3+, NKp46, TRAIL, PD-1, VEGF, and TGFβ2 to gain additional insights into the tumor immune microenvironment at both the two weeks after treatment initiation timepoint and the EOS timepoint, respectively." (PMID 37446056, 2023). "Myofibroblast CAFs (myCAFs) and endothelial TGFBR1 were identified as a potential targets for TGFB2 from basal-like tumor cells." (PMID 37633924, 2023). "The purpose of the present study was to evaluate the clinical prognostic significance of high tumor TGFB2 mRNA levels in pediatric DIPG, as measured by RNAseq." (PMID 36980562, 2023). "Inside the tumor tissue, the three established isoforms of TGFβ, namely, TGFβ1, TGFβ2, and TGFβ3, are released by cancer cells or CAFs." (PMID 38111465, 2023). "Transforming growth factor-beta 2 (TGF-β2) is a cytokine that plays a very important role in tumor initiation, progression, and many other important processes in malignancy." (PMID 36776837, 2023). "DAPK1 can enhance anti-tumor immunology, and DNA is hypermethylated in high WM_Score patients, whilst stromal-activation-related genes such as TGFB2 are hypomethylated." (PMID 37319315, 2023).